IL6 (interleukin 6)
Diseases named in the same sentence as IL6 in open-access papers (continued):
Sharing a sentence is not in itself a finding about the gene and the disease.
anemia (continued). "The work-up and diagnosis of unexplained anemia in the elderly may include the measurement of inflammatory markers such as CRP and erythrocyte sedimentation rate, interleukin-6, and hepcidin levels." (PMID 30836932, 2019). "Some researchers have revealed that Herba Leonuri obviously increased the numbers of erythrocyte, attenuated the levels of EPOR and IL6, inhibited HIF-1α expression, and consequently improved the anemia, which supported its crucial role in the improvement of anemia." (PMID 29551975, 2018). "Here we present the possibility that tocilizumab might be an effective treatment for RA with MDS, especially in those with high levels of IL-6, elevated CRP, and severe anemia." (PMID 29924032, 2018). "Likewise, COPD which is one of systematic inflammatory diseases is generally concomitant with the elevation of IL-1, IL-6 and TNF-a level in circulation inducing the development of anemia." (PMID 30139350, 2018). "In our patient, IL-6 accounts for a variety of clinical symptoms including generalized lymphadenopathy and hepatosplenomegaly, polyclonal hypergammaglobulinemia, increased levels of ESR, CRP and ferritin, anemia, and overproduction of autoantibodies." (PMID 28183278, 2017). "The CRF rats present persistent anemia, without EPO deficiency, with low serum iron and transferrin levels, although iron storage was normal, and unchanged serum IL-6 and hsCRP levels, showing the absence of systemic inflammation." (PMID 26712750, 2015). "We did not measure more accurate markers of inflammation, but several studies have clearly demonstrated that CRP levels positively correlate with the severity of anemia and EPO resistance in CKD patients, and that CRP concentrations closely reflect Interleukin-6 levels." (PMID 25781618, 2015). "Lipopolysaccharide injections in the mice induce an inflammatory response, with upregulation of IL6, an increase in Socs3 mRNA, Crp mRNA and hepcidin mRNA and protein and a decrease in serum iron, but generally do not induce anemia." (PMID 24808863, 2014). "Moreover, SJDBT inhibited a production of IL-6, MCP-1, PYY, and GLP-1 and ameliorated cancer-induced anemia." (PMID 24963216, 2014). "IL-6 was the necessary and sufficient cytokine for the induction of hepcidin during inflammation because IL-6 or hepcidin knockout mice do not develop anemia upon inflammation." (PMID 24878740, 2014). "Anemia in patients with COPD is likely due to a combination of several factors: (i) Elevated cytokines levels, especially Tumor Necrosis Factor alpha (TNF α) and interleukin-6 (IL-6)." (PMID 24564844, 2014). "Furthermore, both IL-6 and TNF-α can induce VEGF production and anemia reportedly impacts angiogenesis via impairment of tissue oxygenation, because hypoxia is a major stimulus for the up-regulation of VEGF." (PMID 24286116, 2013). "Both treatments are effective in treating CKD-induced anemia in pediatrics; however, oral lactoferrin demonstrated superior efficacy as there was a significant change within that group in levels of Hb, RBCs, MCH, iron, RDW-SD, MCHC, IL-6, and GDF-15 before and after treatment." (PMID 39910177, 2025). "Specifically, South American fur seal pups that failed to recover from hookworm-associated anemia had sustained higher concentration of neutrophils, IFN-γ, and IL-6, while those that recovered showed decreases in these markers and increased IL-10 concentration." (PMID 41306959, 2025). "While the use of bLF in women with iron deficiency (ID) or iron deficiency anemia (IDA) decreased IL-6 levels and increased prohepcidin levels, in patients without ID/IDA, bLF did not affect IL-6 levels but increased prohepcidin levels, indicating a selective effect dependent on body iron status." (PMID 40286136, 2025).
anemia (continued). "Anemia of inflammation has been described as usually mild, presenting with erythrocytes of normal size (normocytic) and Hb content (normochromic), decreased serum iron but replete iron stores (ferritin > 100 mg/L), elevation of inflammatory markers (CRP, IL-6), and elevated hepcidin." (PMID 38892681, 2024). "However, despite more severe anemia following CpG injections, circulating levels of IL-6 were not increased in IL-18BP KO as compared with WT mice." (PMID 37074208, 2023). "We found statistically significant differences in hepcidin concentrations between non-anaemia men and men who developed anaemia when we compared hepcidin, IL-6, and TNF-α concentrations between non-anaemia and anaemia patients, as well as men who developed anaemia during their hospitalization." (PMID 36612220, 2022). "However, patients with post-operative anaemia had lower mean hepcidin concentration (x ̄=49.75 ng/mL) and higher mean IL-6 concentration (x ̄=31.54 pg/mL) than non-anaemia patients (x ̄=106.33 ng/mL and x ̄=26.42 pg/mL, respectively)." (PMID 36612220, 2022). "At this stage there is an increase in cytokines such as interleukin (IL)-6 and tumour necrosis factor (TNF)-alpha because of an increased acute phase and chronic inflammation, and additional problems emerge such as subfebrile fever, aches, fatigue, and chronic disease anemia." (PMID 35592192, 2022). "The plasma IL-6 spike in CKDu subjects at G3b is notable as it is a multifunctional cytokine that has modulatory roles on different but overlapping facets of CKD, such as anemia, acute phase response, monocyte differentiation into macrophages, and T cell responses." (PMID 35076512, 2021). "Thus, HIV, its virulent proteins, TB, heroin, cocaine and proinflammatory cytokines including IL-1, IL-6, TNF-α altogether could be responsible for anemia severity among HIV+ TB+ ISUs." (PMID 33911826, 2020). "Also ALD518 (another anti-IL-6 antibody) showed no clinical benefits for NSCLC patients, except for reduction of cancer-associated anemia and cachexia." (PMID 32365499, 2020). "Additionally, all of the criteria to classify abnormal biochemistry (increased CRP or IL6, anemia and low serum albumin) were not available." (PMID 31118043, 2019). "However, no direct correlation of synergistically blocking the IL-6 and IL-8 receptors and hepcidin expression or the effect on cancer-related anemia was reported in this study." (PMID 30641920, 2019). "Other studies have shown elevated levels of cytokines such as IL-6 in cancer patients with anemia, which may contribute to a lack of significant response in erythropoiesis and to an increase in hepcidin expression levels." (PMID 28327200, 2017). "Nevertheless, unlike LCMV infections, both IL-6 upregulation and anemia in this case were found to be independent of IFNγ, suggesting that multiple distinct mechanisms can operate to trigger local IL-6 secretion during different pathogenic inflammatory conditions." (PMID 28163704, 2016). "Our data support the hypothesis that increased hepcidin levels via IL-6 signaling pathways play an etiologic role in cancer-related anemia by confining iron to cellular stores and not allowing exploitation of iron for hematopoiesis." (PMID 27068103, 2016). "However, compared to non-anaemic men, men with anaemia had hepcidin concentrations that were twice as low (x ̄ = 155.97 ng/mL vs. x ̄ = 82.09 ng/mL, respectively), and IL-6 concentrations that were marginally higher (x ̄ = 12.91 pg/mL vs. x ̄ = 15.59 pg/mL, respectively)." (PMID 36612220, 2022). "While higher spontaneous production of IL-8 and IL-6 may reflect the pro-inflammatory status of the mothers, particularly the HIV-infected ones, and may be mediators of the development of anemia, the response to PRR suggest an impact of anemia on the immune response." (PMID 32765436, 2020).
anemia (continued). "However, it was observed a negative correlation between IL-6 levels and neutrophil count, which can reinforce that neutropenia, thrombocytopenia and anemia are not only a consequence of depletion of bone marrow cellularity by Leishmania infiltration but also, a consequence of systemic inflammation." (PMID 30913261, 2019). "Specifically, the investigators considered milder systemic symptoms the consequence of a failure to increase IL-6 levels (with the result of normal baseline values of CRP and ESR, and an absence of anemia)." (PMID 40508840, 2025). "Significant positive correlations were observed between OPG and ferritin, sTfR, sRANKL, CRP, IL-6, RF, and DAS28, and a negative correlation was found with serum iron in the ACD subgroup but not in the combined anemia ACD/IDA subgroup." (PMID 39684440, 2024). "sRANKL was positively correlated not only with sRAGE but with prohepcidin, CRP, IL-6, RF, anti-CCP antibodies, and DAS28 in the ACD subgroup but not in the subgroup with combined anemia (ACD/IDA)." (PMID 39684440, 2024). "On the other hand, the long-term anemia group had higher creatinine, urea, serum IL-6, sFas levels, EPO/Hb, and sFas/eGFR ratio at baseline than the patients without long-term non-anemia." (PMID 37390095, 2023). "Altogether, these data suggest that the IL-6/hepcidin 1 axis and TNF-α are not involved in the anemia observed during CpG-induced MAS." (PMID 37074208, 2023). "In this study, patients in the transfusion group had higher levels of inflammatory biomarkers, such as IL-6 and ferritin, as well as lower TIBC and transferrin levels as biomarkers of anemia, upon ICU admission than those in the non-transfusion group." (PMID 30673726, 2019). "However, pups that did not recover from anemia showed increases in neutrophil count and plasma concentration of IFN-γ and IL-6 relative to their baseline values, whereas pups that recovered had declines in these markers." (PMID 41306959, 2025). "In future studies, the cut-off values, at which hepcidin, IL-6, and CRP concentrations may differentiate future anaemia patients from patients who are not expected to develop anaemia, must be determined." (PMID 36612220, 2022). "In addition, blood levels of anemia-related inflammatory cytokines, including IFN-γ, TNF-α, IL-6 and IL-10, were not affected by the daily administration of 2500 mg TIMEx/kg body weight in both sexes." (PMID 34040996, 2021).
myocardial infarction (499 papers, 2007 to 2026). Gross necrosis of the myocardium, as a result of interruption of the blood supply to the area, as in coronary thrombosis. "We aimed to summarize the pathogenic role of IL-6 in atherothrombosis and myocardial infarction (MI), with focus on novel pathogenic mechanisms and current IL-6 targeted therapy in clinical cohorts." (PMID 41543641, 2026). "suPAR outperforms traditional inflammatory markers, like hsCRP and IL-6, in predicting atherosclerosis, myocardial infarction, and heart failure, suggesting distinct pathogenic pathways." (PMID 41480757, 2026). "Individually, both NETs and IL-6 signaling have been associated with the formation and stabilization of thrombi in myocardial infarction." (PMID 40508157, 2025). "This study identified that acute coronary syndrome patients, particularly those with myocardial infarction, exhibited significantly higher microplastic burden, with associated elevations in inflammatory cytokines such as IL-6 and IL-12p70." (PMID 40169912, 2025). "Among the various cytokines involved, IL-6 is a major pro-inflammatory cytokine associated with organ dysfunction, and high mortality rates in acute myocardial infarction complicated by CS." (PMID 40884675, 2025). "Specifically, IL-6, a proinflammatory cytokine and mediator of cardiovascular risk, is associated with myocardial infarction and heart failure." (PMID 40721314, 2025). "The results demonstrated that colchicine was associated with a significant reduction in hs-CRP and IL-6 levels, as well as a lower incidence of adverse cardiovascular events, particularly myocardial infarction and recurrent myocardial ischemia." (PMID 40688868, 2025). "In population-based studies, circulating IL-6 has been associated with higher risk of incident myocardial infarction, IS and vascular death up to 20 years after the measurement." (PMID 40858837, 2025). "The level of MMP-9 is directly correlated with the activity of fibrinogen, C-reactive protein, and IL-6, which are markers for predicting the risk of myocardial infarction (MI)." (PMID 39335497, 2024). "Elevated IL-6 levels were significantly associated with peripheral artery disease, myocardial infarction, and heart failure, while IL-1β levels were linked to worse outcomes in coronary artery disease and heart failure." (PMID 39057626, 2024). "Meanwhile, CPC has a positive effect against acute myocardial infarction, causing down-expression of phospho-(Ser 536)-NFκB p65 and mRNA synthesis for IL-1β, IL-6, TNF-α, and INFγ." (PMID 39000141, 2024). "Elevated IL-6 levels have been linked to several adverse cardiovascular outcomes, including an increased risk of myocardial infarction, heart failure, and overall mortality in CVD patients." (PMID 39057626, 2024). "Elevated IL-6 levels are associated with an increased risk of myocardial infarction, heart failure, and overall mortality in CVD patients." (PMID 39057626, 2024). "Myocardial and skeletal muscle cells with high levels of IL-1 and IL-6 are exposed to a greater risk of heart attack and rupture of myofibrils, respectively." (PMID 38672567, 2024). "The association between serum interleukin-6 (IL-6) and highly sensitive C - reactive protein (hsCRP) as predictors of the risk factors for Myocardial Infarction." (PMID 38854770, 2024). "Another investigation substantiated that heightened IL-6 levels are linked to worse prognosis in unstable angina and post-acute myocardial infarction scenarios." (PMID 39408157, 2024). "Myocardial damage, heart failure, and mortality are linked to high levels of circulating IL-6 during and immediately after an acute myocardial infarction." (PMID 35997998, 2023). "The data revealed that, at week 5 post myocardial infarction, MA treatment was associated with significant reductions in circulating levels of both IL-6 and TNF-α compared to levels after treatment with vehicle." (PMID 36263604, 2023).
myocardial infarction (continued). "Interleukin-6 (IL-6) is linked to an increased risk of cardiovascular events, specifically myocardial infarction." (PMID 37893238, 2023). "In a study involving 14 916 apparently healthy men, elevated levels of interleukin 6 (IL6) were associated with an increased risk for future myocardial infarction, which suggests a role for cytokine‐mediated inflammation in the early stages of atherogenesis." (PMID 37927482, 2023). "Plasma IL-6 is elevated after myocardial infarction (MI) and is associated with increased morbidity and mortality." (PMID 36943408, 2023). "Increased levels of inflammatory markers like C-reactive protein (CRP) and interleukin-6 (IL-6) are closely linked to a higher risk of heart attacks." (PMID 38292979, 2023). "In contrast, persistently elevated IL-6 levels in patients with acute myocardial infarction are associated with low left ventricular ejection fraction and HF." (PMID 35888173, 2022). "An early study found that elevated circulating IL-6 levels in patients >65 years were associated with a history of heart attack." (PMID 35821823, 2022). "IL-27′s enhancement of TNF-α mediated upregulation of adhesion molecules and pro-inflammatory IL-6 in blood monocytes of patients with acute myocardial infarction (MI) makes it high CVD risk associated." (PMID 35327515, 2022). "Interleukin-6 (IL-6) is associated with an increased risk of adverse cardiovascular events, especially myocardial infarction, since IL-6 favors the onset of unstable plaque atherosclerosis or increases the inflammatory rate of already present plaques." (PMID 35328730, 2022). "Inflammasome (NLRP3) activation, subtypes of lymphocytes, interleukin 6, and some inflammatory biomarkers, are associated with larger infarct size and impaired ventricular function after myocardial infarction." (PMID 35837017, 2022). "A recent study consisting of myocardial infarction patients showed that higher IL-6 levels and a lower sIL-6r:IL-6 ratio early after presentation was associated with larger infarct size and decreased cardiovascular function." (PMID 36164462, 2022). "In patients after acute myocardial infarction IL6 levels have been associated with increased cardiovascular mortality during a 3-year follow-up period independently of other inflammatory parameters." (PMID 35621838, 2022). "The polymorphism of IL-6 is also observed at the cardiac level when its dual role is initially protective by limiting myocyte injury during acute myocardial infarction." (PMID 35888173, 2022). "Clinical studies have shown a correlation between the area of myocardial necrosis and the plasma IL-6 levels in patients with acute myocardial infarction, suggesting an association between IL-6 levels and MIRI." (PMID 33428604, 2021). "This evidence suggests that there is a positive correlation between IL-6 and the risk of myocardial infarction." (PMID 34504432, 2021). "The allele is also associated with a higher risk of coronary heart disease and myocardial infarction, both of which are related to a higher expression of IL-6 from peripheral blood mononuclear cells." (PMID 34865658, 2021). "Next, we set out to determine the underlying association between heart attack and triglycerides while controlling for TNFα, IL6 and HDL-C." (PMID 33510184, 2021). "IL-6 is independently associated with the risk of major adverse cardiovascular events, cardiovascular and all-cause mortality, myocardial infarction, heart failure, and cancer mortality in patients with stable CHD." (PMID 34725557, 2021). "In prior studies, higher IL-6 levels in healthy males were associated with future myocardial infarction incidence." (PMID 34861824, 2021). "Perhaps the most important inflammatory markers associated with ischemia and reperfusion lesions in acute myocardial infarction are IL-6 and TNF-α." (PMID 33238444, 2020).